Y_RNA (Y RNA )
Gene: Miscellaneous RNA gene on chromosome 4 (39,710,085 to 39,710,176, reverse strand). Ensembl gene ENSG00000252975.
Homologues: Orthologues: chimpanzee Y_RNA (100% identical). Paralogues in human: Y_RNA (88% identical), Y_RNA (87% identical), RNY3 (86% identical), RNY3P1 (86% identical), Y_RNA (86% identical), Y_RNA (85% identical), Y_RNA (84% identical), RNY3P11 (83% identical), Y_RNA (83% identical), RNY3P14 (82% identical), RNY3P16 (82% identical), RNY3P7 (82% identical), and 88 more.